IL2 (interleukin 2)
Diseases named in the same sentence as IL2 in open-access papers (continued):
Sharing a sentence is not in itself a finding about the gene and the disease.
lymphoma (continued). "First, we transduced the IL-2 indicator cell line MO7e with lentiviral expression vectors encoding the wild-type form of JAK3, the constitutive-active, and lymphoma-associated variant JAK3-A572V, or the JAK3-R840C variant, and analyzed IL-2-dependent growth at increasing IL-2 concentrations." (PMID 29375547, 2017). "The production of sIL-2Rα by lymphoma cells suggests that supplementation with IL-2 may be a valid treatment strategy; however, the dual role of IL-2 in expanding both cytotoxic effector cells as well as Tregs complicates its efficacy as a therapy on its own." (PMID 25941795, 2015). "However, since IL-2 is a cytoplasmic protein and cannot be used as a surface marker for cell sorting, these cells are technically difficult to isolate from lymphoma tissues." (PMID 23675235, 2011). "Additionally, IL-2 enhanced lymphoma cell survival by overcoming kinase inhibitor U0126-induced growth arrest and apoptosis." (PMID 23675235, 2011). "Interestingly, immunostaining of lymphoma tumor tissues showed IL-2 protein expression in background cells within tumor tissue, but not in ALCL cells." (PMID 23675235, 2011). "Although miR-26a has not been implicated in the regulation of IL-2, we examined whether miR-26a downregulation in MDV-transformed chicken lymphoma cell lines do affect IL-2 expression." (PMID 20441582, 2010). "Therefore, we were interested in evaluating the potential of IL-2 and IL-12 transduced lymphoma cells for their ability to stimulate and activate immunologic effector cells." (PMID 15485577, 2004). "Some more obvious cytokines such as IL-2, IL-6, IL-7, and IL-15 have a direct link with T-cell lymphoma progression, and these cytokines’ expression levels have the potential to be used as biomarkers especially to predict the developmental stage of T-lymphoma tumor cells." (PMID 37746258, 2023). "Moreover, WASp KO mice controlled growth of A20 lymphoma cells that naturally produced IL-2." (PMID 27477778, 2016). "In other studies, mice with inoculated lymphoma or mastocytoma treated intraperitoneally with IL-2 achieved a 70–90% CR, cattle with ocular squamous cell carcinoma treated with peritumoural IL-2 achieved a 69% CR, and horses with sarcoid tumours achieved a 14% PR and 43% CR with intratumoural IL-2." (PMID 23927575, 2013). "Therefore, expression of IL-2 and IL-12 in lymphoma cells may be used to further increase their sensitivity towards adoptively transferred CD8+ NKT cells in the future." (PMID 15485577, 2004). "Anyway, to propose the use of Bre–Ved–ZA ADC to trigger the activation of Vδ2 T-cells against lymphoma cells, this ADC should be further supplemented by an activating cytokine such as IL2 in our experimental system." (PMID 38786084, 2024). "And the STAT3 (rs744166), IL2 (rs2069762), IL10 (rs1800871), and PARP1 (rs907187) manifested a significant relationship with the peripheral blood counts in lymphoma patients." (PMID 37329186, 2023). "We activated the TCR/CD3 signaling in the IL-2 Jurkat cells using OKT3 anti-human CD3 antibody and co-incubated them for 6 hours with various lymphoma lines as the source for co-stimulatory signals." (PMID 33411730, 2021). "Comparable cytokine levels (granulocyte macrophage colony-stimulating factor GM-CSF, interferon [IFN]-γ, IL-2, and tumor necrosis factor alpha [TNF-α]) were detected in all CAR T cell samples upon exposure to CD19-positive lymphoma cells." (PMID 33575430, 2021). "Reduction of EBV-specific IL-2+ CD4+ and CD8+ T cells was found in HIV+ patients in stages 2, 3, and with lymphoma, which was evident of the first stages of T-cell exhaustion." (PMID 30337929, 2018). "Sixteen patients with lymphoma received, 12–14 days post-transplantation, LAK cells generated from PBMCs incubated with IL-2 for 5 days." (PMID 26029215, 2015). "We previously reported that IL-2 deprivation induced acid sphingomyelinase-mediated (ASM-mediated) ceramide elevation and apoptosis in an NK/T lymphoma cell line KHYG-1." (PMID 25855965, 2015).
lymphoma (continued). "The simultaneous synergistic action of IL2 and IL12 will re-activate both types of cytolytic effector cells, T and NK cells, in the lymphoma lesion." (PMID 23028547, 2012). "We here generated and analyzed a panel of antibody-cytokine fusion proteins to target IL2 and IL12 toward CD30+ H/RS lymphoma cells in order to locally activate both an adoptive and innate immune response." (PMID 23028547, 2012). "Our findings demonstrate that IL-2 signaling plays a functional role in ALCL cells, and enhances lymphoma cell survival by increasing activation of the ERK1/2 pathway." (PMID 23675235, 2011). "IL-2 and/or IL-12 transduced lymphoma cells were co-cultured with PBMC, which were assayed for their cytolytic activity against unmodified lymphoma cells." (PMID 15485577, 2004). "An EuTDA cytotoxicity assay was used to compare cytotoxic activities of IL-2 and/or IL-12 stimulated PBMC against unmodified lymphoma cells." (PMID 15485577, 2004). "In addition, an enhanced effect was observed when mice with lymphoma were treated with S. Typhimurium LVR01 and interleukin-2 (IL-2)." (PMID 38116133, 2023). "A combination of rituximab and EDB-specific IL-2 immunocytokine eradicated tumors in multiple lymphoma xenografts with no apparent toxicity, while rituximab combined with IL-2 only delayed progression." (PMID 33803078, 2021). "In mice engrafted with CD19+ Raji lymphoma cells, those infused with CD19-directed CAR T-cells rapidly developed CRS, and administration of dasatinib significantly decreased levels of IFN-γ, GM-CSF, IL-2, and TNF-α and protected mice from fatal CRS." (PMID 33643299, 2020). "Here we report on the effects of extra- and intracellular cNMPs and their extracellular degradation products on HuT-78 Sézary lymphoma cells in three different functional readouts, namely T cell receptor (TCR)-mediated IL-2 production, apoptosis, and proliferation." (PMID 32313990, 2020). "Laboratory examinations indicating malignant lymphoma such as soluble interleukin-2 were all negative." (PMID 30984398, 2019). "Neither E.G7 lymphoma nor OT-II TCH cells constitutively produced IL-2 in the cultures, therefore, any detected cytokine production would represent the outcome of DC presentation of peptide and T cell recognition." (PMID 31602007, 2019). "IL-2 was not quantifiable in cultures of patients with lymphoma or EBV+HIV+, and IL-10 was only detectable in 15/55 (27%) patients." (PMID 30337929, 2018). "However, because interleukin-2 (IL-2) is essential for clonal expansion of KHYG-1 cells, this cell line is a useful model to investigate the mechanism by which NK/T lymphoma cells undergo programmed cell death." (PMID 25855965, 2015). "Peripheral blood mononuclear cells of healthy donors and post-transplant lymphoma patients were stimulated with or without lunasin in the presence of IL-12 or IL-2." (PMID 24363024, 2014). "Given that TGF-β up-regulates IL-2 production, we wanted to test whether IL-2 signaling plays a role in TGF-β-mediated regulation of T cell differentiation in the lymphoma microenvironment." (PMID 23555036, 2013). "As recently reported, B-cells from a canine high-grade lymphoma could successfully be stimulated with concentrations of 1.0 μM DSP30 and 100 U/ml IL-2 for 72 h resulting in an adequate number of metaphases." (PMID 22761949, 2012). "NK1.1+ lymphoma-like T cells isolated from the liver had a markedly reduced ability to produce IFN-γ and IL-2 compared to NK1.1− lymphoma-like cells and HMNCs of non-lymphoma dnTGFβRII IL-6−/− mice, while such difference was not seen in the spleen." (PMID 23145171, 2012). "Since IL-2 affects ALCL cells, we investigated the potential source of IL-2 for the lymphoma cells." (PMID 23675235, 2011). "IL-2 is produced mainly by activated T helper CD4+ lymphocytes and is one of critical cytokines that control the proliferation and clonal expansion of transformed lymphoma cells." (PMID 20441582, 2010).
lymphoma (continued). "Interestingly, immunostaining of ALCL tumor tissues showed IL-2 protein expression in background cells but not in lymphoma cells." (PMID 40507248, 2025). "Consistent with previous studies, for example, IL-2 can regulate STAT4 to enhance the function of natural killer cells, and it can lead to the down-regulation of STAT4 protein during the treatment of lymphoma, which results in STAT4 defects and affects the therapeutic effect." (PMID 41010015, 2025). "Several clinical trials are testing the combination of CAR T-cell therapy with IL-2 (NCT00924326, NCT00019136, NCT04119024, NCT03098355), revealing enhanced persistence of CAR T-cells and durable remissions in vivo in different tumor entities such as lymphoma, ovarian cancer and melanoma." (PMID 34445701, 2021). "However, using cell lines as inoculum an IL‐2 support does barely reflect “real world” inter‐patient heterogeneity of the lymphomas because the subcutaneously injected cells did not disseminate beyond the injection site." (PMID 30484952, 2019). "Finally, we investigated whether exogenous C2-ceramide mimics IL-2(−)-mediated CTSB activation, XIAP degradation, and caspase-dependent NK/T lymphoma cell apoptosis." (PMID 25855965, 2015). "To mobilize both adoptive and innate immune cells for an anti-tumor attack we fused the pro-inflammatory cytokines IL2 and IL12 to an anti-CD30 scFv antibody in a dual cytokine fusion protein to accumulate both cytokines at the malignant CD30+ Hodgkin/Reed-Sternberg cells in the lymphoma lesion." (PMID 23028547, 2012). "Increased IFN-γ secretion that is associated with NK and T cell activation, in concert with delivered IL2 and IL12 is moreover expected to shift the Th2 imbalance in the lymphoma lesion towards Th1 reactivity which might counteract the T cell hypo-responsiveness in Hodgkin's lymphoma." (PMID 23028547, 2012). "In addition, molecular and immunochemical studies revealed that IL-2 protein was expressed in the background cells of lymphoma tissues, but not in the ALCL cells themselves." (PMID 23675235, 2011). "Third, fortune dictated that we would end up focusing on human T cell malignancies because of our discovery of IL-2 which allowed us to grow significant numbers of such cells in many but not all instances (not all T cell leukemias or lymphomas respond to IL-2)." (PMID 15743526, 2005). "Since this study is a retrospective study, the exact contribution of IL-2 can not be ascertained given the co-administration of DEX, which is a known therapeutic agent in lymphomas." (PMID 34872514, 2021). "We compared the outcome of the patients included in the DLI-NK trial to a historical control cohort of patients treated in the same center who did not receive IL-2 NK (n = 61), including 27 AML, 16 lymphoma, 12 myeloma, 5 ALL, and 1 CLL." (PMID 34071607, 2021). "Cultures exposed to the polyclonal stimulus (PMA + ionomycin) showed that CD4+ T cells from HIV+ patients with lymphoma were not able to produce TNF-α, IFN-γ, and/or IL-2 (p < 0.05)." (PMID 30337929, 2018).
psoriasis (102 papers, 2006 to 2025). An autoimmune condition characterized by red, well-delineated plaques with silvery scales that are usually on the extensor surfaces and scalp. "This is highlighted by the observation that low dose IL-2 significantly improves the clinical manifestations of psoriasis associated with amplification of the percentage of immunosuppressive Tregs." (PMID 40868162, 2025). "Regarding inflammatory markers, a low-calorie KD in 30 patients with psoriasis led to decreased IL-1β and IL-2 levels, along with 10% weight loss and 50% reduction in the PASI score." (PMID 38473723, 2024). "Subsequently, PKA activates the cAMP response element-binding protein (CREB), exerting control over pivotal genes associated with psoriasis, such as IL-2, IL-6, IL-10, and TNFα." (PMID 38258034, 2023). "Psoriasis is an inflammatory condition that is associated with excessive secretion of proinflammatory cytokines (IL-2, IL-6, IL-8, IL-12, IL-19, IL-22, IL-23, IFN-γ and TNF-α) into blood as well as dermal tissue." (PMID 37266425, 2023). "Our findings suggest that psoriasis is associated with higher IL-2 levels, possibly because IL-2 is engaged in its initiation and development." (PMID 37883350, 2023). "IL-2 and IL-17A have been reported to be responsible for activating pathogenic inflammation in a number of inflammatory skin diseases such as psoriasis." (PMID 25705127, 2015). "A study performed in 114 psoriasis patients and 281 controls from Korea showed that rs2069762 (G allele) in IL2 conferred a risk of developing the disease, mainly in late-onset psoriasis." (PMID 24069534, 2013). "In a Korean population (114 patients and 281 controls), the rs2069762 (G allele) in IL2 conferred a risk of psoriasis, mainly in the late-onset group." (PMID 24069534, 2013). "Taking the correlation between IL-2 and the risk of psoriasis as an example, the meta-analysis uses SMD as the effect size; the Q test for heterogeneity (I2 = 93.1% >50%, P <0.001) indicates high heterogeneity among studies and thus a random effect analysis was performed." (PMID 37883350, 2023). "IL-36 activates the pro-inflammatory transcriptional factor nuclear factor kappa B (NFκB), induces T Helper cell type 1 (Th1) responses by enhancing cell proliferation and IL2 secretion and is implicated in the inflammatory response from skin epithelial cells in psoriasis." (PMID 31921151, 2019). "Furthermore, a previous study identified that three SNPs from chromosome 4q27, containing genes for IL-2 and IL-21, were involved in the genetic susceptibility to psoriasis and psoriatic arthritis." (PMID 24944624, 2014). "Therefore, our hypothesis in the present study is that anti-IL-2/IL-2 complex in psoriasis-like model will expand higher Treg cells in vivo than free IL-2, resulting in mitigation of the associated inflammation." (PMID 41254515, 2025). "In psoriasis, Th1‐type cytokines such as IFN‐γ and IL‐2 are significantly increased, while the levels of Th2‐type cytokines like IL‐10 are relatively low, further promoting the immune response related to psoriasis." (PMID 40599237, 2025). "After low-dose IL-2 treatment, the clinical manifestations of psoriasis improved, and the PASI 50 and PASI 75 were 68.89% and 22.22% at week 24, respectively." (PMID 37596509, 2023). "Low-dose IL-2 combination therapy effectively improved the clinical manifestations of psoriasis but decreased the inflammatory indicators of the disease activity, with no apparent side effects." (PMID 37596509, 2023). "This study focused on the status of circulating CD4+ T subsets and the clinical efficacy of low-dose IL-2 therapies in psoriasis." (PMID 37596509, 2023). "After administering low-dose IL-2 for psoriasis, it also decreased the inflammatory indicators of disease activity, including the leukocyte count, neutrophil count, ESR, CRP, and NLR in serum after treatment." (PMID 37596509, 2023).
psoriasis (continued). "To investigate new concepts for the treatment of psoriasis, we observed the inflammatory and immunological indices of patients with psoriasis before and after treatment with low-dose IL-2 to clarify the clinical efficacy and safety." (PMID 37596509, 2023). "For example, use of basiliximab, a chimeric IL-2 mAb, was effective for the treatment of severe psoriasis." (PMID 36675037, 2023). "The pooled SMD from the meta-analysis was 1.29 (95% CI: 0.61–1.97; P < 0.001), showing that the levels of IL-2 in external serum were significantly greater in patients with psoriasis compared to healthy controls." (PMID 37883350, 2023). "This exerts control over the genes that can be associated with psoriasis to start inflammatory cytokine secretion (e.g., IFN-γ, TNF-α, IL-2, IL-12, IL-23)." (PMID 38258034, 2023). "Given that the IL-2 response gene signature was particularly enriched in the skin, we decided to evaluate the effects of IL-2 molecules in a mouse model of psoriasis." (PMID 37809101, 2023). "The pro-inflammatory mediators associated with psoriasis are IL1B, IL2, IL6, IL12, IL15, IL17, IL18, and IL20." (PMID 37569685, 2023). "Low-dose IL-2 treatment significantly amplified the percentage of Treg cells and restored the Th17 and Treg immune balance in psoriasis (P < 0.001)." (PMID 37596509, 2023). "We would encourage researchers to examine the diagnostic and prognostic role of IL1-β, TNF-α, IL-2 and IFN-γ in different psoriasis clinical forms." (PMID 34209865, 2021). "We noted a positive correlation between TNF-α and NO concentrations in unstimulated saliva of patients with hyposalivation, as well as between IL-2 and NO contents in unstimulated saliva of psoriasis patients with normal saliva secretion." (PMID 32164227, 2020). "Serum levels of TNF-α, IFN-γ, IL-2, IL-6, IL-8, IL-18, IL-22, chemerin, lipocalin-2, resistin, sE-selectin, fibrinogen, complement 3, and adiponectin correlate with psoriasis and can be used as potential biomarkers for psoriasis and response to the treatment." (PMID 29416693, 2018). "The pooled serum levels of TNF-α, IFN-γ, IL-2, IL-6, IL-8, IL-18, IL-22, chemerin, lipocalin-2, resistin, sE-selectin, fibrinogen and C3 were higher in psoriasis patients compared with healthy controls (all P < 0.05)." (PMID 29416693, 2018). "As expected, the majority of CD3+CD8− T cells produced TNFα and IL-2; there was no reduction in TNFα with either carnosol or curcumin treatment, and only a small reduction in IL-2 production was seen in curcumin treated psoriasis PBMC." (PMID 29980703, 2018). "Psoriasis, PsA and rheumatoid arthritis are characterised by the secretion of several pro-inflammatory cytokines such as IL-2, IL-6, IL-8, IFN-γ and TNF-α." (PMID 29587639, 2018). "In psoriasis, T-cells (both CD4+ and CD8+) are known to cause low production of Th2 cytokines (IFNγ, TNFα, and IL-2) and high production of Th1 cytokines (IL-4, IL-6 and IL-10), leading to polarization of the type 1 pathway." (PMID 26849645, 2016). "Circulating levels of interferon- (IFN)-γ, interleukin- (IL)-1RA, IL-2, and IL-23, and LL-37 were significantly higher in patients with psoriasis than in healthy controls." (PMID 25197165, 2014). "For CD8+ T cells, we observed that the production of IL-17A, IL-22, IFN-gamma, TNF-alpha, and IL-2 were higher in lesional skin than unaffected skin of psoriasis patients." (PMID 23468834, 2013). "Linear regression showed that IL-2, IL-6 and IL-12 levels predicted 66% of corticosterone levels, which were selectively increased in psoriasis mice subject to PSD." (PMID 23226485, 2012). "In psoriasis, the cytokine expression profile is selectively skewed toward a T1 (i.e., IL-2, TNF-α, IL-12, IFN-γ) and away from a T2 (i.e., IL-2, IL-5, IL-6, IL-10, IL-13) pattern." (PMID 20040934, 2008). "Therefore, we aimed to compare the immunomodulatory effects of anti-IL-2/IL-2 complex to free IL-2 on induced psoriasis-like skin inflammation induced in mice by the TLR7 agonist imiquimod." (PMID 41254515, 2025).